IDO1 (indoleamine 2,3-dioxygenase 1)
Diseases named in the same sentence as IDO1 in open-access papers (continued):
Sharing a sentence is not in itself a finding about the gene and the disease.
tumor (continued). "Moreover, we identified a certain number of highly expressed IDO1 tumor cells and named them IDO1_fib." (PMID 38443340, 2024). "Moreover, IDO1 reintroduction negated the suppressive impact of FLI1 KO on tumor growth and T cell exhaustion." (PMID 38816360, 2024). "However, the so far developed strategies of IDO1 inhibition disappointed their postulated anti-tumor efficacy, suggesting the need of developing more efficient ways of blocking IDO1-mediated pathways." (PMID 38333210, 2024). "Our combination strategy of TPME remodeling synergized with immune‐metabolic blockade can establish an inflammatory tumor immune niche via disrupting the IDO1/Kyn/AhR axis‐mediated immune escape, which exerts effective tumoricidal immune activity to inhibit postsurgical ccRCC recurrence." (PMID 38884220, 2024). "Ultimately, these data highlight what appears to be direct cellular interaction between both tumor and immunosuppressive myeloid-lineage cells, often positive for PD-L1 or IDO1, with infiltrating lymphoid populations, often positive for PD-1, within the 5-year deceased cohort." (PMID 39333065, 2024). "Therefore, by producing IAA, PA communicates with M2 macrophages to promote their expansion or survival in tumor foci and drive IDO1 expression." (PMID 38540186, 2024). "Post-treatment, the tumor microenvironment showed immunomodulatory changes, including altered macrophage infiltration and significant gene expression changes related to inflammation and immune response, such as IDO1, IL-6, TNF, CD209, and FOXP3." (PMID 39765586, 2024). "Imatinib achieves its tumor-killing effect by inhibiting IDO1 expression through the KIT pathway." (PMID 38443340, 2024). "Moreover, IDO1 inhibition was detected, together with efficient accumulation in the tumour environment and a long circulation time." (PMID 39273286, 2024). "IDO1 inhibitors that could restore the anti-tumoral function of T-cells and shift the tumor microenvironment from immunosuppressive to immunogenic are currently under investigation in various clinical trial settings." (PMID 38706595, 2024). "Our findings indicated a significantly (p < 0.05) higher expression of protein biomarkers associated with the presence and activity of immune cells, including CD45, CD3, CD68, CD163, CD11c, CD8, HLA-DR, CD40, PD-L1, and IDO1, in the tumor compartments of patients with CR compared to those with PD." (PMID 39049036, 2024). "In vivo, knockdown of TRIM28 significantly inhibited the tumor growth and overexpression of IDO1 and SRF both could reverse proliferation inhibited by TRIM28 knockdown." (PMID 38947391, 2024). "Combining our data, previous in vitro studies using LLC cells and in vivo reports, it is suggested that IDO1-expressing tumor cells could induce the tube formation of adjacent vascular cells, regardless of the cell type or the originating site of the tumor." (PMID 39065567, 2024). "Similarly, in mice with IDO1 and IL-6 knockout, a decreased probability of tumor metastasis and improved survival rate were observed." (PMID 38883986, 2024). "IDO1 then functions as a nutrient scavenger, starving the effector T cells from the tumour microenvironment of tryptophan, as well as inducing differentiation of tumour protective T cells (Treg) via its immunosuppressive reaction product, kynurenine." (PMID 39282472, 2024). "This implies that IDO1 has a high degree of tumor prediction capacity." (PMID 38539263, 2024). "We may conclude here that PA dysbiosis causes IAA upregulation, which promotes IDO1 expression and Kyn production by regulating macrophages and CD8+ T cells with potential effects on immune surveillance in tumor foci." (PMID 38540186, 2024).
tumor (continued). "Furthermore, tumor cells alter interferon signaling to prioritize the production of immunosuppressive molecules like PD-L1 and IDO1 and to increase the expression of ISGs." (PMID 39223632, 2024). "The two altered-excluded tumors contained 2% and 60% of IDO1-positive tumor cells, respectively." (PMID 39061522, 2024). "Moreover, the activity of IDO1 is involved in promoting neovascularization, thereby further supporting tumor growth, while expression of TDO by tumor-associated pericytes suggests a similar role for TDO." (PMID 39211039, 2024). "Similarly, also in the altered-immunosuppressive carcinomas additional factors of immunosuppression appear likely due to the wide range of IDO1-positive tumor cells." (PMID 39061522, 2024). "Besides its presence in tumor cells, IDO1 is also expressed by various cells residing in the TME or tumor-draining lymph nodes, including dendritic cells, MDSCs, macrophages, endothelial cells, fibroblasts and mesenchymal stem cells." (PMID 39211039, 2024). "c-Myc induces the expression of PD-L1 and IDO1, promoting tumor immune evasion." (PMID 39223632, 2024). "Compared with shVector cells, IDO1+ cells showed more progressive tumor growth, strong IDO1 expression, a low relative Trp concentration, a high relative [Kyn]/[Trp] ratio, and a low CD8+T proportion in TIL; however, in shIDO1 cells, these phenomena in IDO1+ cells were reversed." (PMID 38540186, 2024). "Notably, elevated IDO1 expression at the tumor invasion front correlates with disease progression, serving as an independent prognostic marker for CRC." (PMID 38646539, 2024). "In particular, the combination of IDO1 inhibitors with PD-1 antibodies could drastically enhance the objective response rate of tumor therapy." (PMID 38882349, 2024). "Variable percentages of IDO1-positive tumor cells were detected in 90 (94%) carcinomas." (PMID 39061522, 2024). "Moreover, IDO1 overexpression in tumor cells has been shown to promote tumor growth in vivo, which is associated with decreased infiltration of effector T cells, and increased numbers of regulatory T cells and MDSCs." (PMID 39211039, 2024). "Additionally, we observe an increased expression of STING in tumor-sparse regions, which is known to increase IDO1 activity." (PMID 39001353, 2024). "Finally, tumor infiltrating dendritic cells and macrophages also express the enzyme indoleamine 2,3-dioxygenase 1 (IDO), which metabolizes tryptophan into kyneurenines." (PMID 39346924, 2024). "Furthermore, IDO1 promotes the expansion and suppressive capacity of MDSCs, and indirectly recruits them to the tumor through the action of IDO1-induced regulatory T cells." (PMID 39211039, 2024). "Considering that previous studies have demonstrated that photothermal therapy treatment could induce the overexpression of IDO1, we evaluated the expression of IDO1 in tumours and LNs." (PMID 37076492, 2023). "In our study, MUC16 induced high expression of immunosuppressive factors such as IL-6, IL-8, PD-L1 and IDO1 in neutrophils, which might result in the weakness of tumor cell-killing ability for NK cells." (PMID 37644468, 2023). "Hence, the finding that IDO1 is overexpressed in many tumors together with the delineation of its role in tumor immune resistance made IDO1 an attractive drug target in oncology." (PMID 37122718, 2023). "Indoleamine-2.3-dioxygenase 1 (IDO1) is a cytosolic enzyme that catalyzes essential amino acid tryptophan to kynurenine, whose metabolites will lead to the suppression of T cells and are responsible for tumor immune escape." (PMID 37106400, 2023). "Among them, an increase in tumor-derived IDO1 promotes resistance to ICIs therapy." (PMID 37304265, 2023). "This added complexity means that therapeutic approaches should be guided by an informed analysis of the particular relevance of IDO1 expression within the tumor type being targeted because defeating immune tolerance will have different treatment implications than eliminating neovasculature." (PMID 37182174, 2023).
tumor (continued). "Furthermore, IDO1-mediated tryptophan metabolism, tumor-derived PGE2, and oxysterol receptor LXR transcription factor also maintain the immunoinhibitory functions of TAMs." (PMID 38008741, 2023). "Thus, expression of inhibitory checkpoints in the tumor microenvironment of OS pulmonary metastases, such as TIM-3, Lag-3, and IDO1, are associated with immunosuppression." (PMID 37329384, 2023). "Furthermore, co-culture experiments indicated that the expression of IDO1 inhibited the proliferation of activated T lymphocytes in the tumor microenvironment, consequently affecting the development and occurrence of tumors." (PMID 37345200, 2023). "In addition, these workers showed the presence of IDO1 staining in tumor microenvironmental cells in six FL samples." (PMID 37108483, 2023). "Interferons are potent IDO1 inducers and part of the IDO1 expression by tumor cells might be attributed to IFN-γ." (PMID 36879122, 2023). "Given the distinct influence of ERO1a inhibition on the hypoxic tumor secretome and the greater impact of IDO1 inhibition on myeloid signaling, the combined effect of ERO1a and IDO1 inhibition at the same single treatment concentration was investigated for their immune-related biological pathways." (PMID 38187398, 2023). "However, at this point, very little is understood about the extrinsic IFN-independent signals that control IDO1 expression in tumor cells." (PMID 37196768, 2023). "High IDO1 expression in the tumor microenvironment of OSCC correlates with poor patient prognoses." (PMID 36831659, 2023). "For example, macrophage with indoleamine 2,3-dioxygenase 1 (IDO1) pathway activation might conversely limit the efficacy of PD-1 because of the immunosuppressive tumor environment." (PMID 36873946, 2023). "This line of reasoning may inform expectations regarding the involvement of IDO1 in different tumor contexts." (PMID 37182174, 2023). "Therefore, treatment strategies against IDO1 would not only directly target tumor cells, but also result in the downregulation of immunosuppressive signals." (PMID 37108483, 2023). "Moreover, epigenetic modifications and changes in chromatin structure make tumor cells more likely to upregulate IDO1 than normal cells in response to IFN signals." (PMID 37670034, 2023). "Our studies further support the potential therapeutic efficacy of dual IDO1/TDO2 inhibition as a part of immuno-therapeutic treatment that enhances tumor immune surveillance and blocks tumor metabolism-related survival mechanisms in platinum-resistant NSCLC tumors." (PMID 37226257, 2023). "Therefore, while the ability of IDO1 to support inflammatory neovascularization can contribute to the establishment of a tumor-promoting inflammation, it can also underpin the vascular pathophysiology of non-malignant diseases as well." (PMID 37182174, 2023). "Therefore, intense efforts have been to design and develop selective inhibitors of the catalytic activity of IDO1 as a goal to enhance anti-tumor immune responses." (PMID 37122718, 2023). "Inhibition of GCH1 by 2,4-diamino-6-hydroxypyrimidine could block IDO1 activity, halt tumor growth, and enhance the tumor response to anti-PD-1 immunotherapy." (PMID 37040510, 2023). "Furthermore, higher IDO1 expression was significantly correlated with advanced tumour stage and metastasis." (PMID 38062922, 2023). "IFN-γ also induces tumor-repopulating cells (TRCs) to enter dormancy by an IDO1-Kyn-aryl hydrocarbon receptor (AhR)-p27 dependent pathway in TME with TRCs expressing high levels of IDO1 and AhR." (PMID 37380989, 2023). "Besides suppressing anti-tumor immune responses, tumoral IDO1 is involved in tumor vascularization and lymphangiogenesis." (PMID 37817770, 2023). "Therefore, IDO1 inhibition was a target for anti-cancer therapy in order to restore tumor immunity, and several IDO1-inhibitors were currently tested in vitro as well as in clinical trials." (PMID 36798123, 2023).
tumor (continued). "Chronic inflammation is usually accompanied by the secretion of immunosuppressive factors such as ROS, ARG1, PGE2, PD-L1, IDO1, etc., resulting in promoting the formation of an inhibitory immune microenvironment and inhibiting tumor-killing effect of CD8+ T cells and NK cells." (PMID 37644468, 2023). "However, a phase III trial assessing their clinical benefit failed, prompting us to revisit the role of IDO1 in tumor cells under T cell attack." (PMID 36812891, 2023). "The increases of IDO-1 expression in the apical or basal extrusion of human PDAC implied that the tumor milieu might drive IDO-1 expression in extruding cells." (PMID 36517670, 2023). "However, it is crucial to note that using IDO-1 inhibitors as a monotherapy approach promotes tumor growth." (PMID 37626777, 2023). "The elevated metabolite levels in ascites may arise from the proximity of this fluid to the tumor as well as the presence of tumor and immune cells, likely expressing IDO1 and/or IL4I1, in the ascites itself." (PMID 36765849, 2023). "The results indicated that IDO1 was contributed to the proliferation and migration of tumor cells, which may function as an oncogene in EC." (PMID 37903782, 2023). "In addition to IDO1, it has been long known that tumours can suppress immunogenic signals by activating the signal transducer and activator of transcription 3 (STAT3) signalling, which ultimately suppresses DCs maturation." (PMID 37454231, 2023). "IDO1 expression has been reported in several cancers in which IDO1-positive cells in the tumor microenvironment may facilitate tumor immune escape through the upregulation of Tregs." (PMID 37108483, 2023). "In IDO1-overexpressing tumors, Treg cells promote tumor growth in cooperation with M2-like TAMs29." (PMID 37394584, 2023). "For a tumor that develops in the absence of IDO1-associated inflammation, the selective pressure exerted by immunoediting would still select for elevated tryptophan catabolism as a component of the escape process." (PMID 37182174, 2023). "In tumor, aberrant activation of IDO1 and TDO leads to the inhibition of anti-tumor immunity." (PMID 37540213, 2023). "More complex immunocompetent models will be required for formal testing of our hypothesis in vivo that the positive effect that IDO1 inhibition may have on CD8 T cells is counteracted by the tumor protection described here." (PMID 36812891, 2023). "TDO may likely be the prime substitute enzyme as it is not only expressed constitutively but has also been suggested to replace IDO1 as the driver for the KP during metastases in a tumour metastasis mouse model study." (PMID 37041200, 2023). "Additionally, recent findings indicate that IDO1 also promotes tumor neovascularization by subverting local innate immunity." (PMID 37182174, 2023). "At harvest, tumor tissues were collected and assayed for IDO1/TDO2 and IDO2 protein expression." (PMID 37226257, 2023). "IDO1 also promotes tumor neoangiogenesis through the expression of interferon-γ (IFN-γ) and IL-6." (PMID 37626654, 2023). "Additionally, the 1-MT greatly decreased the Treg cells in the tumour compared with NS group, indicating the IDO1 inhibitor indeed inhibited the infiltration of Treg cells." (PMID 37076492, 2023). "Although nonenzymatic functions of IDO1 are implicated in the regulation of the immune response, most studies have focused on a large array of Trp metabolites that drive crosstalk between tumor, parenchymal, and immune cells or between immune cells." (PMID 37394584, 2023). "This variability may reflect different types or magnitudes of effect of PD-L1 and IDO1 in different tumor environments." (PMID 37296860, 2023). "In addition, a specific peptide vaccination directed against IDO1 can be combined with anti-PD-1 therapy to inhibit tumor cell growth." (PMID 37342333, 2023).
tumor (continued). "Based on these mechanisms, it can be speculated that elevated IDO1 levels can serve as a potential biomarker, highlighting decreased immune cell surveillance and tumor progression." (PMID 36879122, 2023). "While there is limited information on the patient cohort, potential explanations for these different observations could be due to proportion of the subtypes of BrCa and/or the percentage of patients with IDO1 overexpressing-tumours enroled in these studies." (PMID 37041200, 2023). "In this study, we found that Abrine as an IDO1 inhibitor has an inhibition effect on immune escape, and its combination therapy with immune checkpoint inhibitor anti-PD-1 antibody exerted a better anti-tumor effect." (PMID 37334368, 2023). "Thus, rather than acting as a fundamental driver of either inflammation or tumorigenesis, IDO1 acted as a modifier of the inflammatory milieu, changing its metabolic character and rendering it more supportive of tumor development." (PMID 37182174, 2023). "IDO1 is expressed by tumor cells, tolerogenic DC cells, MDSCs cells and fibroblasts." (PMID 37427115, 2023). "As most of human cancers, including BrCa, overexpress IDO1, the validation of IDO1 inhibitor efficacy in enhancing anti-tumour immune activity could be translated for clinical use." (PMID 37041200, 2023). "IDO1 allows tumour cells to escape the immune system by two main mechanisms." (PMID 36980527, 2023). "Moreover, heightened IDO1 expression correlates with tumor differentiation, distant metastasis, and an advanced clinical stage." (PMID 37999261, 2023). "Hence, studies usually combine both techniques to provide an accurate overview of IDO1 activity in the tumour and to assess if its activity is inhibited when an inhibitor is applied." (PMID 37041200, 2023). "Consequently, a TRP-stripped tumour microenvironment mediated by an overactive tumoral IDO1/TDO will induce mid-G1 phase arrest in T cells." (PMID 37041200, 2023). "Indeed, the targeted chemotherapeutic drug for leukemia, imatinib, has been shown to enhance anti-tumor immunity by activating cytotoxic T cells and suppressing Tregs in an IDO1-dependent manner." (PMID 37631380, 2023). "The primary focus of IDO1 inhibitor activity was to locally restore tryptophan availability to create a permissive environment for anti-tumor T cell proliferation and function, which we now know is only one regulatory pathway activated by regulated tryptophan metabolism." (PMID 37196768, 2023). "We further validated the association between IDO1 and HSV-1 in VX-2 tumor cells." (PMID 37296221, 2023). "Moreover, increased IDO1 is thought to reduce the availability of tryptophan in the tumor microenvironment, thereby decreasing the immune response and ultimately promoting tumorigenesis." (PMID 36755301, 2023). "Therefore, studies have focused on developing IDO or TDO inhibitors to improve the anti-tumor effects of immune cells, and IDO1, IDO2 and TDO inhibitors have already been summarized." (PMID 37277776, 2023). "In physiological conditions, the activity of IDO-1 is minimal, but it is highly induced by the following: interferons γ, α, and β; bacteria lipopolysaccharides; viruses; proinflammatory interleukins (IL-1, IL-6, and IL-8); and tumor cells." (PMID 36980311, 2023). "Moreover, IDO1 controls also a multi-pronged anti-ferroptotic death pathway, which plays a pivotal role in tumour suppression in TME." (PMID 36161514, 2023). "As a consequence, upregulation of IDO1 expression in tumor cells, programmed cell death 1 (PD-1) in CD8+ T cells and forkhead box P3 (FOXP3) in CD4+ T cells occur, overall impairing CD8+ T cells proliferation and promoting the conversion of CD4+ T cells to Tregs." (PMID 37122718, 2023). "In addition, in a series of tumor cell lines, IDO1 expression was shown to be driven by an autocrine positive feedback loop via the activation of AhR by kynurenine." (PMID 36422996, 2023).